ZFX (zinc finger protein X-linked)
Description:
Probable transcriptional activator.
Synonyms: ZNF926; MRXS37
Tractability: PROTAC: ubiquitination databases record sites on it; its protein half-life has been measured.
Target class: Transcription factor
Gene: Protein-coding gene on chromosome X (24,148,976 to 24,216,255, forward strand). Ensembl gene ENSG00000005889.
Subcellular location: Nucleus
Subcellular location (Human Protein Atlas): Nucleoplasm; Nucleoli
Gene Ontology:
Molecular function: DNA-binding transcription activator activity, RNA polymerase II-specific; RNA polymerase II cis-regulatory region sequence-specific DNA binding; DNA binding; metal ion binding
Biological process: positive regulation of transcription by RNA polymerase II; regulation of transcription by RNA polymerase II; regulation of DNA-templated transcription
Cellular component: chromatin; nucleus
Homologues: Orthologues: chimpanzee ZFX (99% identical), macaque ZFX (99% identical), rabbit ZFX (98% identical), guinea pig ZFX (97% identical), mouse Zfx (95% identical), rat Zfx (95% identical). Paralogues in human: ZFY (93% identical), ZNF711 (59% identical), ZFAT (22% identical), PRDM15 (18% identical), ZBTB11 (17% identical), ZNF304 (16% identical), ZSCAN2 (16% identical), ZNF792 (16% identical), ZNF551 (15% identical), ZNF480 (15% identical), ZNF256 (15% identical), ZNF583 (15% identical), and 26 more.
Diseases named in the same sentence as ZFX in open-access papers:
ZFX is named in the same sentence as 55 diseases in open-access papers, as found by Europe PMC text mining. Sharing a sentence is not in itself a finding about the gene and the disease. The quoted sentences say what the papers report.
breast carcinoma (11 papers, 2015 to 2025). "The expression of ZFX variants were evaluated in the breast cancer cell lines; MCF7, SK-BR-3, MDA-MB-231, and pluripotent embryonic carcinoma; NCCIT." (PMID 29753316, 2019). "Our data also showed that the expression of ZFX variant 1/3 significantly increased in the luminal A subtype of breast cancer, whereas the expression of ZFX variant 4 was elevated in the triple-negative subtype of breast cancer." (PMID 29753316, 2019). "These ZFX variants were expressed in embryonic stem cells (NCCIT) as well as in breast cancer cell lines." (PMID 29753316, 2019). "We investigated the expression of ZFX variants in a series of breast cancer tissues and cell lines using quantitative PCR." (PMID 29753316, 2019). "Also, the expression of ZFX variant 5 increased in both triple-negative and the luminal A subtypes in comparison to other subtypes of breast cancer." (PMID 29753316, 2019). "Therefore, we investigated the possible expressions of ZFX-spliced variants in the breast cancer cell lines and 47 breast cancer samples by using specific primer sets." (PMID 29753316, 2019). "Furthermore, our results revealed that the ZFX variant 4 expression was higher in high-grade breast cancer tissues compared to the low-grade ones (p < 0.05)." (PMID 29753316, 2019). "In conclusion, our data show that the ZFX-spliced variants have a distinctive expression pattern in different types of breast cancer, and the variants may contribute to the tumorigenesis of breast cancer." (PMID 29753316, 2019). "Therefore, based on our results, the different expression patterns of ZFX variants in different stages of breast cancer may be involved in the progression and metastasis of breast cancer cells." (PMID 29753316, 2019). "Overexpression of zinc finger protein, X-linked (ZFX) has been shown to promote cell growth and metastasis in laryngeal squamous cell carcinoma, glioma, non-small cell lung cancer, gastric cancer, oral squamous cell carcinoma, gallbladder cancer and breast cancer." (PMID 27411336, 2016). "To assess the correlation of RICTOR, UGCG, and ZFX in cancer cells, we analyzed publicly available single-cell RNA sequencing datasets from breast cancer patients (GSE176078)." (PMID 40934285, 2025). "Although our study is focused on luminal breast cancer, we have shown that ZFX also regulates UGCG expression in other cancer cell lines." (PMID 40934285, 2025). "To find the association between ZFX and UGCG in luminal breast cancer patients, we analyzed the TCGA-BRCA and METABRIC patient gene expression datasets." (PMID 40934285, 2025). "To further validate the association of ZFX and UGCG in breast cancer patients, we quantified the expression of UGCG and ZFX by immunohistochemical (IHC) analysis in tumor samples of all subtypes (N = 90)." (PMID 40934285, 2025). "Zinc finger protein X-linked (ZFX) was identified as a target gene of miR-138-5p, which can be overexpressed by NEAT1 in breast cancer cells." (PMID 37310654, 2023). "To determine if ZFX contributes to regulation of the promoters to which it is bound, we performed RNA-seq analysis after knockdown of ZFX by siRNA in prostate and breast cancer cells." (PMID 29429977, 2018). "Even though the expression of ZFX variant 5 was higher in the triple-negative and luminal A subtypes rather than HER2 type and luminal B subtypes, there is not significant association between ZFX variant 5 expression levels and breast cancer subtypes." (PMID 29753316, 2019). "We further evaluated the expression level of variants in tumor vs. non-tumor marginal tissues of 47 patients with breast cancer at the mRNA level to investigate the possible role of ZFX-spliced variants in tumorgenesis." (PMID 29753316, 2019). "Our data suggest that the expression of ZFX-spliced transcripts varies between different types of breast cancer and may contribute to their tumorigenesis process." (PMID 29753316, 2019).
breast carcinoma (continued). "Similarly, expression of ZFX is high in advanced invasive breast cancers and knockdown of ZFX reduces the proliferation rate of breast cancer cells." (PMID 29429977, 2018). "Similarly, high ZFX expression is frequently detected in primary breast cancer tissues with metastatic potential, implying a role in tumor progression." (PMID 26967242, 2016). "Hence, ZFX-spliced transcripts could be considered as novel tumor markers with a probable value in diagnosis, prognosis, and therapy of breast cancer." (PMID 29753316, 2019). "In line with our findings in human cell culture and mouse models, we observe an elevated expression of RICTOR, ZFX, and UGCG in Indian luminal breast cancer tissues and in TCGA and METABRIC datasets." (PMID 40934285, 2025). "HER2 regulates the proliferation of breast cells, and the HER2 gene plays a key role in the development of breast cancer via cell proliferation and survival through AKT and MAPK pathways, which are affected by ZFX overexpression." (PMID 29753316, 2019). "For example, ZFX overexpression has been observed in prostate cancer, gastric cancer, human gliomas, non-small-cell lung cancer (NSCLC), breast cancer, and so on." (PMID 25916205, 2015). "Six variants had no additional breast-cancer-affected carriers identified in the pedigrees they were originally found in (in genes KIF15, TMEM192, MUC5AC, TEP1, ZFX, and TNN)." (PMID 38136396, 2023). "It has been reported that ZFX knockdown in diverse tumor types including gliomas, NSCLC, LSCC, breast cancers, and gastric cancer all led to hypophosphorylation of Akt, extracellular signal-regulated kinase 1/2 (ERK1/2), or MEK1/2 except for ERK2 hyperphosphorylation in breast cancer cells." (PMID 25916205, 2015).
gastric cancer (11 papers, 2014 to 2021). A primary or metastatic malignant neoplasm involving the stomach. "For example, lncRNA small nucleolar RNA host gene 20 (SNHG20) induces gastric cancer progression via upregulating zinc finger protein X-linked (ZFX) expression by absorbing miR-495-3p." (PMID 32156248, 2021). "ZFX promotes laryngeal squamous cell carcinoma, hepatocellular carcinoma, gastric cancer, bladder cancer, and pancreatic cancer and is associated with poor patient prognosis." (PMID 32760226, 2020). "In a recent gastric cancer study, ZFX was shown to be closely linked with the MAPK signaling pathway, which contributes to CRC development." (PMID 26967242, 2016). "ZFX variants 1 and 3 (isoform I) have been found to be overexpressed in the diffused type of gastric cancer as well as different tumor grades, whereas the ZFX variant 5 transcript (isoform III) is heterogeneous in gastric specimens and has a positive correlation with tumor size." (PMID 29753316, 2019). "For example, lncRNAs FTX facilitated the progression of gastric cancer via sponging miR-144 to elevate ZFX." (PMID 33298078, 2020). "Further, knockdown of ZFX has been reported to inhibit cellular proliferation in human laryngeal squamous cell carcinoma, gastric cancer, malignant glioma, non-small cell lung carcinoma and prostate cancer." (PMID 25594030, 2014). "Moreover, miR-144 also targets zinc finger X-chromosomal protein (ZFX), and downregulation of miR-144 and consequent upregulation of ZFX expression promotes the bone marrow metastasis of gastric cancer cells." (PMID 26826553, 2016). "Increased expression of ZFX negatively correlates with microRNA-144 expression and may contribute to bone marrow metastasis in gastric cancer." (PMID 26967242, 2016). "In addition, ZFX targeting has been shown to effectively inhibit the growth of gastric cancer cells in vitro and in vivo." (PMID 26967242, 2016).
glioma (10 papers, 2015 to 2023). A benign or malignant brain and spinal cord tumor that arises from glial cells (astrocytes, oligodendrocytes, ependymal cells). "The zinc finger and X-linked transcription factor (ZFX) is associated with proliferation, tumorigenesis, and poor patient survival in a variety of human cancers, and maintains self-renewal and tumorigenic potential of glioma stem like cells by upregulating c-Myc expression." (PMID 36850002, 2023). "Among them, lncRNA NFIA-AS2 was previously shown to promote glioma progression by regulating the miR-655-3p/ZFX axis." (PMID 36061188, 2022). "For instance, lncRNA NFIA-AS2 was shown to be highly expressed in glioma and promoted the proliferation and migration of glioma cells via modulating the miRNA-655-3p/ZFX axis." (PMID 33282010, 2020). "Of note, a current study has demonstrated that ZFX upregulated c‐Myc expression in glioma stem cells by binding to a specific sequence on the promoter region of c‐Myc." (PMID 28156061, 2017). "Although ZFX could directly transcriptional activated c‐Myc expression in the fraction of glioma stem‐like cells, our current data reveal a novel molecular mechanism by which ZFX controls c‐Myc expression in HCCs." (PMID 28156061, 2017). "Another group reported that ZFX could bind to a certain sequence on human c‐Myc promoter to upregulate its expression, thus maintaining the stem‐like phenotypes and tumorigenic potential of glioma stem cells." (PMID 28156061, 2017). "Mutations in XIE genes USP9X, NLGN4x, PLXNB3 (involved in axonal guidance and glioma invasion), SYAP1, SRPX2, and ZFX (ZFX-SMARCA1 fusion) occurred in non-MN1-BEND2, predominantly female cases." (PMID 35440587, 2022).
colorectal cancer (6 papers, 2016 to 2022). A primary or metastatic malignant neoplasm that affects the colon or rectum. "ZFX is a transcriptional activator of that has been linked to oncogenic processes in numerous cancer types and has been correlated with aggressive tumor phenotypes and poor survival in colorectal cancer." (PMID 33413550, 2021). "The expression of several zinc finger proteins, such as ZEB1, ZFX and PRDM1, has been reported to be associated with the survival of colorectal cancer patients." (PMID 33892786, 2021). "High expression of ZFX promotes tumor growth of colon cancer cells and colorectal cancer patients with high ZFX expression have poorer overall and disease-free survival." (PMID 29429977, 2018).
gallbladder cancer (6 papers, 2015 to 2025). "ZFX has been implicated in various cancers including pancreatic, gastric, hepatocellular carcinoma, malignant glioma, and gallbladder cancer." (PMID 31310241, 2019). "In addition, in gallbladder cancer, baicalein suppressed metastasis through Zinc finger protein, X-linked (ZFX)." (PMID 35656442, 2022). "In gallbladder cancer models (GBC-SD and NOZ), liensinine induces G2/M arrest and apoptosis through inhibition of the zinc finger protein X-linked (ZFX)-induced PI3K/AKT pathway." (PMID 41154606, 2025). "So we are curious about whether the effect of baicalein on gallbladder carcinoma cells is connected to ZFX expression." (PMID 25617627, 2015). "Thus, the data suggested that the ZFX protein might participate in baicalein-induced cell apoptosis and anti-metastasis in gallbladder carcinoma cells." (PMID 25617627, 2015).
prostate carcinoma (5 papers, 2014 to 2020). A carcinoma that arises from epithelial cells of the prostate gland. "For example, prostate cancer tissues exhibit significantly higher ZFX expression than benign prostatic hyperplasia and adjacent tissues and siRNA-mediated knockdown of ZFX suppresses the proliferation of prostate cancer cells and reduces the number of colonies in colony forming assays." (PMID 29429977, 2018). "However, less than half of the bound promoters show responsiveness to loss of ZFX and ZNF711 in the knockout HEK293T cells or after knockdown of all three family members in 22Rv1 prostate cancer cells (data not shown)." (PMID 32406922, 2020).
hepatocellular carcinoma (4 papers, 2017 to 2020). A malignant tumor that arises from hepatocytes. "We observed that the elevated expression of both ZFX and epithelial cell adhesion molecule (EpCAM) was associated with aggressive clinicopathological features and indicated poor prognosis in patients with hepatocellular carcinoma (HCC)." (PMID 28156061, 2017). "Interestingly, we noticed that knockdown of ZFX suppressed the expression of several important β‐catenin target genes such as c‐Myc, c‐Jun, and cyclin D1 in hepatoma cells, whereas enforced expression of ZFX upregulated these downstream effectors both in mRNA and protein levels." (PMID 28156061, 2017). "Here, we found that the content of ZFX was further enhanced in nonattached hepatoma spheroids compared with the monolayer cultured cells." (PMID 28156061, 2017).
laryngeal squamous cell carcinoma (4 papers, 2014 to 2020). A squamous cell carcinoma that arises from the larynx. "Studies from our lab also showed that ZFX is involved in human laryngeal squamous cell carcinoma (LSCC), a subgroup of cancer of HNSCC, and ZFX knockdown impaired the cell proliferation and induced apoptosis in LSCC Hep-2 cells." (PMID 25916205, 2015). "In consistent with the role of C2H2-ZF proteins in cancer development, previous studies from our lab have shown that ZFX is aberrantly upregulated in human laryngeal squamous cell carcinoma and ZFX knockdown impaired cancer cell proliferation and apoptosis." (PMID 25916205, 2015). "As both tongue SCC and laryngeal squamous cell carcinoma belong to HNSCC, here we examined the expression status of ZFX and unraveled significant expression differences between tumors and adjacent normal tissues derived from tongue SCC patients." (PMID 25916205, 2015).
parathyroid adenomas (4 papers, 2014 to 2025). "Using whole exome and direct sequencing of parathyroid adenoma DNA samples, we identified recurrent somatic mutations in the ZFX gene." (PMID 25594030, 2014). "Somatic variants in the ZFX gene have been found in human sporadic parathyroid adenomas." (PMID 40779536, 2025). "In addition to MEN1 and CCND1, other genes that participate in the development of parathyroid adenoma include those encoding cyclin-dependent kinase inhibitors, along with CTNNB1, EZH2, ZFX, GCM2, and CASR." (PMID 30832348, 2019).
triple-negative breast carcinoma (4 papers, 2019 to 2021). An invasive breast carcinoma which is negative for expression of estrogen receptor (ER), progesterone receptor (PR), and human epidermal growth factor receptor 2 (HER2). "CCAT1 promotes proliferation and migration of triple-negative breast cancer cells via downregulating miRNA miR-218 and activating the expression of protein ZFX." (PMID 33745450, 2021). "CCAT1 promotes the progression of triple-negative breast cancer by suppressing miR-218/ZFX signaling." (PMID 33193573, 2020). "For example, miR-218 was found to negatively regulate the zinc finger transcription factor (ZFX), therefore suppressing triple-negative breast cancer progression." (PMID 31986487, 2020).
tongue squamous cell carcinoma (3 papers, 2015 to 2019). A squamous cell carcinoma that arises from the tongue. "Our results provide evidence suggesting that ZFX overexpression is associated with the development of tongue SCC and ZFX knockdown is a potential treatment for tumor suppression." (PMID 25916205, 2015). "And, our discovery of ZFX overexpression in tongue SCC samples expanded our understanding about molecular mechanisms of tongue SCC." (PMID 25916205, 2015). "So, our future studies will focus on the upstream/downstream pathways of ZFX in vitro and in vivo to provide more insights into the underlying mechanisms about HNSCC or tongue squamous cell carcinoma." (PMID 25916205, 2015). "So, our results provide confidential evidence that ZFX is quite a promising target for tongue SCC treatment." (PMID 25916205, 2015). "Furthermore, ZFX knockdown impeded cell proliferation, impaired colony formation ability, and lead to cell cycle arrest while induced cell apoptosis in human tongue squamous cell carcinoma cell line Tca-8113." (PMID 25916205, 2015). "ZFX expression in human tongue SCC samples was significantly higher than that in normal adjacent tissues, which implicated that ZFX might be a pathological factor involved in human tongue SCC development." (PMID 25916205, 2015). "It should be noticed that though ZFX functions have been investigated in multiple cancers, very little research focused on the roles of ZFX in HNSCC or tongue squamous cell carcinoma." (PMID 25916205, 2015).
autism (2 papers, 2023 to 2025). Persistent deficits in social interaction and communication and interaction as well as a markedly restricted repertoire of activity and interest as well as repetitive patterns of behavior. "Future studies will determine how ZFX’s transcriptional regulation of autism risk genes contributes to the FPE in autism, based on comparing ZFX and ZFY in diverse in vitro and in vivo contexts." (PMID 40964017, 2025). "We recently showed that ZFX is a key modulator of autism-associated transcriptional programs in human neural progenitor cells." (PMID 40964017, 2025). "Genes exhibiting such a behaviour included the zinc-finger protein ZFX and the histone demethylase KDM5C which is linked to intellectual disability and autism." (PMID 36802379, 2023). "Autism genes are strongly represented amongst these paired genes, with two (NLGN4Y, USP9Y) expressed from Chr Y, and seven (DDX3X, KDM5C, KDM6A, NLGN4X, TBL1X, USP9X, and ZFX) from Xi." (PMID 40964017, 2025).